PBRM1 (polybromo 1)
Diseases named in the same sentence as PBRM1 in open-access papers (continued):
Sharing a sentence is not in itself a finding about the gene and the disease.
adenosquamous carcinoma (1 paper, 2025). A carcinoma composed of malignant glandular cells and malignant squamous cells. "IHC analysis of 12 human pancreatic squamous cell carcinoma or adenosquamous carcinoma samples revealed that the expression of ΔNp63 was upregulated in all the samples and that PBRM1 expression was lost in 83% of those." (PMID 40454484, 2025).
ampullary carcinoma (1 paper, 2022). "Notably, except for the PBRM1 gene, all other genes were previously reported in other ampullary carcinoma cohorts." (PMID 36178086, 2022).
breast tumor (1 paper, 2015). "In human breast tumor, functional analyses revealed that truncated mutation of PBRM1 induced loss of cell cycle regulatory activity." (PMID 25978027, 2015).
carcinoma of the pancreas (1 paper, 2025). "Second, we demonstrated that Pbrm1 ablation in established PDAC converted the tumor grade from well-differentiated to poorly differentiated PDAC or undifferentiated pancreatic carcinoma in vivo." (PMID 40454484, 2025). "Further investigations are needed to determine whether vimentin inhibitors have therapeutic effects in patients with PDAC with low PBRM1 expression, poorly differentiated PDAC, squamous molecular subtype PDAC, or undifferentiated pancreatic carcinoma." (PMID 40454484, 2025).
clear-cell carcinoma (1 paper, 2021). "Loss of 3p in clear-cell carcinoma targets driver genes of VHL, PBRM1, SETD2 and BAP1 with collateral deletion of a series passenger genes, amongst which certain genes harbor indispensable functions to maintain cancer cell viability." (PMID 34593007, 2021).
colorectal tumor (1 paper, 2025). "To further examine the effect of the PBRM1 mutation on the therapeutic sensitivity of PD1-1 antibody in colorectal tumor cells, we introduced humanized PD-1 mice (BALBc-hPD1)." (PMID 40093909, 2025). "Next, to investigate whether the PBRM1 mutation regulates the tumor microenvironment through exosome secretion, we constructed a colorectal tumor cell line with PBRM1 and SMase2 mutations." (PMID 40093909, 2025). "We clarified the effect of PBRM1 on the sensitivity of colorectal tumors to anti-PD1 immunotherapy by constructing a subcutaneous tumor model in BALB/c mice." (PMID 40093909, 2025). "However, in vitro CCK8 or plate cloning and in vivo subcutaneous tumor assays in BALB/C mice showed that PBRM1 mutations did not affect the proliferation of colorectal tumor cells." (PMID 40093909, 2025).
duodenal tumour (1 paper, 2022). "Similarly, in this study, in vitro cell experiments showed that downregulation of PBRM1 expression could significantly promote the proliferation and migration of duodenal tumour cells and play an important regulatory role in EMT." (PMID 36178086, 2022).
endocervical adenocarcinoma (1 paper, 2024). An adenocarcinoma that arises from the endocervix. "We found a robust NRF2 response to PBRM1 mutations in CESC, endocervical adenocarcinoma, and ESCA." (PMID 38358974, 2024).
endometriosis (1 paper, 2024). The growth of functional endometrial tissue in anatomic sites outside the uterine body. "Collectively, our investigations of PBRM1 offer a conceptual framework for understanding abnormal endometrial homeostasis and unraveling the nature of these signals, with implications for diagnosis and hormone therapy of nonreceptive endometrium in endometriosis-related infertility." (PMID 38426493, 2024).
esophageal squamous cell carcinoma (1 paper, 2016). Esophageal squamous cell carcinoma (ESCC) is a type of esophageal carcinoma (EC) that can affect any part of the esophagus, but is usually located in the upper or middle third. "As for esophageal squamous cell carcinomas (ESCCs), somatic mutations have been detected for ARID1A, ARID2, and PBRM1 by exome-sequencing." (PMID 26812616, 2016).
glioma (1 paper, 2023). A benign or malignant brain and spinal cord tumor that arises from glial cells (astrocytes, oligodendrocytes, ependymal cells). "We demonstrate that H3K27M gliomas show increased protein levels of the SWI/SNF complex ATPase subunits SMARCA4 and SMARCA2, and the PBAF component PBRM1." (PMID 37094128, 2023). "We demonstrate that a PROTAC tool compound AU-15330 that simultaneously degrades the ATPases SMARCA4 and SMARCA2 and PBRM1 selectively kills H3.3K27M but not H3WT glioma cell lines." (PMID 37094128, 2023).
hepatic carcinomas (1 paper, 2022). "Moreover, a cooperative manner of frequent joint inactivation of ARID2, PBRM1 and BAP1 in the subtype of hepatic carcinomas may contribute to malignancy." (PMID 36178086, 2022).
liposarcoma (1 paper, 2018). A usually painless malignant tumor that arises from adipose tissue. "In our study we also noted deleterious mutations in 7 other genes (CTNNB1 (R151H), MECOM (R208C), ZNF536 (T688M), EML4 (W729L), CSMD3 (P627S), PBRM1 (N639K), PPP1R3A (C788Y)) that have also not been described previously in WD/DD liposarcoma." (PMID 29731991, 2018).
lymph node metastasis (1 paper, 2022). "In addition to loss/attenuation of PBRM1 expression, tumor size, depth of invasion, histological grade, lymph node metastasis, clinical stage, MSI, sTIL, and iTIL were statistically significant factors for survival time." (PMID 35928964, 2022).
malignant mesothelioma (1 paper, 2020). A malignant neoplasm of the pleura or peritoneum, arising from mesothelial cells. "The WDPMs lacked the alterations involving BAP1, SETD2, NF2, CDKN2A/B, LASTS1/2, PBRM1, and SMARCC1 that are frequently found in malignant mesotheliomas." (PMID 32545767, 2020). "Indeed, our most important finding is the lack of alterations involving BAP1, SETD2, NF2, CDKN2A, PBRM1, and SMARCC1 genes consistently mutated or deleted in malignant mesotheliomas." (PMID 32545767, 2020).
nasopharyngeal carcinoma (1 paper, 2022). A carcinoma arising from the nasopharyngeal epithelium. "Here, the authors show that EBV-encoded miRNAs EBV-miR-BART11 and EBV-miR-BART17-3p upregulate PD-L1 expression in nasopharyngeal carcinoma and gastric cancer by targeting FOXP1 and PBRM1." (PMID 35165282, 2022).
ovarian carcinoma (1 paper, 2021). A malignant neoplasm originating from the surface ovarian epithelium. "Other SWI/SNF altered cancers that are dependent on EZH2 include SS18-SSX translocated synovial sarcoma, ARID1A-mutated ovarian cancer, SMARCA4-mutated lung and ovarian cancers, and PBRM1-mutated renal cancers." (PMID 34617019, 2021).
pancreatic undifferentiated carcinoma (1 paper, 2025). "We also evaluated 6 resected specimens of undifferentiated carcinoma of the pancreas by immunostaining of PBRM1." (PMID 40454484, 2025). "Five of the 6 pancreatic undifferentiated carcinoma specimens had low PBRM1 expression, a rate higher than that of well- or moderately differentiated PDAC." (PMID 40454484, 2025).
papillary renal cell carcinoma (1 paper, 2021). A rare subtype of renal cell carcinoma, arising from the renal tubular epithelium and showing a papillary growth pattern, which typically manifests with hematuria, flank pain, palpable abdominal mass or nonspecific symptoms, such as fatigue, weight loss or fever. "As PBRM1 alterations are not very common in papillary renal cell carcinoma, its significance in terms of a potential biomarker remains to be elucidated." (PMID 35251119, 2021).
pleural mesothelioma (1 paper, 2022). A neoplasm that arises from the mesothelial cells of the pleura. "In comparison, in the TCGA dataset (cBioportal), with only pleural mesothelioma cases, 7% of the patients harbour an alteration in the PBRM1 gene." (PMID 36138075, 2022). "In our cohort, PBRM1 was altered in 6.8% of pleural mesothelioma and in 15.8% peritoneal tumours." (PMID 36138075, 2022).
psychotic disorder (1 paper, 2013). An abnormal condition of the mind that involves a loss of contact with reality. "The meta-analysis between the current and previous GWAS results showed that rs2251219 in Polybromo1 (PBRM1) was significant on genome-wide association level (P = 5×10−8) only for BD (P = 9.4×10−9) and psychosis (P = 2.0×10−10)." (PMID 23967141, 2013). "Only two SNPs (rs2709722 in SP8 and rs2251219 in PBRM1) within the psychosis set remained significant after the multiple comparison correction (corrected P = 0.037 and 0.048 for rs2709722 and rs2251219, respectively)." (PMID 23967141, 2013). "We found 3p21.1 (including PBRM1, strong linkage disequilibrium made it difficult to pinpoint the risk genes) and SP8 as risk loci for BD, SCZ and psychosis." (PMID 23967141, 2013). "In conclusion, we found two loci, PBRM1 (and neighboring genes) and SP8, that were replicated in psychotic disorders in a Japanese population." (PMID 23967141, 2013).
renal tumours (1 paper, 2017). "Altogether, these data indicate that the combined loss of Vhl and Pbrm1 within mouse tubular epithelia is sufficient for the development of renal neoplasias closely resembling the human disease." (PMID 29229903, 2017).
sarcoma (1 paper, 2022). A usually aggressive malignant neoplasm of the soft tissue or bone. "We also note the unexpected finding that UAS (n = 14), a rare sarcoma subtype, had oncogenic alterations in genes encoding subunits of the SWI/SNF chromatin remodeling complex in 43% of patients, with ARID1A and PBRM1 most frequently affected." (PMID 35705560, 2022).
skull base tumor (1 paper, 2022). "This PDX model was obtained from a primary skull base tumor previously operated and defined by a PBRM1 variant (c.599C>G)." (PMID 35326637, 2022).
synovial sarcoma (1 paper, 2025). "Disruption of Arid1a or Arid1b (both CBAF-specific) retains synovial sarcoma character, while Smarcb1 (PBAF- and CBAF-specific) or Pbrm1 (PBAF-specific) disruption does not, although all accelerate SS18::SSX-driven tumorigenesis in mice." (PMID 41423472, 2025).
thymic adenocarcinoma (1 paper, 2017).
thymoma (1 paper, 2024). A neoplasm arising from the epithelial cells of the thymus. "Individual genes specific to certain subtypes include BCOR in Type A thymoma, PBRM1 in Type AB thymoma, and BRD4 in Type B2 thymoma." (PMID 38338833, 2024).
tubular adenocarcinoma (1 paper, 2021). An infiltrating adenocarcinoma in which the malignant cells form tubular structures. "Notably, the excluded case of tubular adenocarcinoma and case 13 both expressed HepPar1 and had loss of PBRM1." (PMID 33506327, 2021).
tumor (301 papers, 2012 to 2026). "The strong correlation between hypoxic status and PBRM1 mutations (P < 0.01) in ccRCC patients suggests a link between these factors in tumor progression." (PMID 41584042, 2026). "Among the three genes, the loss of SETD2 is typically a subclonal event, whereas the loss of PBRM1 or BAP1 usually occurs as a clonal event earlier in tumor progression." (PMID 41602827, 2026). "Through next-generation sequencing (NGS) analysis of circulating tumor DNA (ctDNA) and tumor tissue DNA (ttDNA) from these patients, mutations in PBRM1, SETD2, and ROS1 were frequently detected in both ctDNA and ttDNA of non-responders." (PMID 41602395, 2026). "Collectively, these data demonstrate that PBRM1 expression is inversely associated with high tumor grade, high recurrence rate, poor prognosis, and the squamous molecular subtype in human PDAC." (PMID 40454484, 2025). "BAP1, a 3p tumor suppressor, correlates with high-grade and sarcomatoid or rhabdoid morphology, while PBRM1 and BAP1 mutations are largely mutually exclusive, BAP1-mutant tumors tending toward greater aggressiveness." (PMID 41426798, 2025). "Most patients with RCC have a deletion of chromosome 3p and genomic alterations in the Von Hippel–Lindau (VHL) tumor suppressor allele, accompanied by the subsequent loss of other tumor suppressor genes, including PBRM1, SETD2, BAP1, and/or KDM5C." (PMID 41440218, 2025). "More importantly, recent studies have shown that mutations in PBRM1 are closely associated with poor tumor prognosis and immunotherapeutic sensitivity." (PMID 40093909, 2025). "A genome‐scale CRISPR‐Cas9 screen to identify mechanisms of tumor cell resistance to killing by cytotoxic T cells identified the loss of over 100 genes, including PBRM1, ARID2, and BRD7, as sensitizing events to T cell‐mediated killing." (PMID 41387924, 2025). "PBRM1 loss sensitizes tumor cells to interferon-γ-mediated killing, complementing the neoantigen-driven immunogenicity of POLD1 mutations." (PMID 40661943, 2025). "PBRM1 inactivation is the second most frequent mutation in ccRCC and is intricately linked to tumor development and variable responses to immune checkpoint blockade (ICB)." (PMID 41315192, 2025). "Given this role, PBRM1 is recognized as a tumor suppressor in ccRCC; however, mutations or loss of PBRM1 are frequently observed in ccRCC." (PMID 41338163, 2025). "The CDX model with PBRM1 mutations had the lowest tumor growth rate compared to that of models with other genetic mutations (P < 0.01)." (PMID 40856833, 2025). "Low PBRM1 expression is associated with high tumor grade, high recurrence rate, poor prognosis, and the squamous molecular subtype of human PDAC." (PMID 40454484, 2025). "Pbrm1 loss in preexisting PDAC shifted the tumor grade from a well- to a poorly differentiated state and elevated vimentin expression." (PMID 40454484, 2025). "Previous published studies on patient tumor samples have reported that PBRM1 mutations, usually truncating ones, lead to a loss of PBRM1 function." (PMID 41440218, 2025). "Simultaneously, PBRM1 loss has been associated with enhanced response to immune checkpoint blockade, potentially due to modulation of the tumor immune microenvironment." (PMID 41395625, 2025). "At the somatic level, PBRM1 mutations have been associated with a less immunogenic tumor microenvironment and upregulated angiogenesis and have suggested more limited benefit from immunotherapy." (PMID 38652565, 2024). "Multiple studies confirm that PBRM1 deficiency can enhance sensitivity to immune checkpoint inhibitors by altering the tumor immune microenvironment and enhancing immune-related gene expression." (PMID 39777351, 2024).
tumor (continued). "We and others have found that PBRM1 missense mutations cluster within its six bromodomains and noted that select PBRM1 bromodomain missense variants exhibit reduced protein stability, Kac binding, and tumor suppressor function." (PMID 38460939, 2024). "In our study, we identified both tumor intrinsic (PBRM1/SETD2 mutations) and extrinsic (IFN-γ and TLS gene signature) components correlating with response to ICT in mccRCC." (PMID 39606482, 2024). "Inactivation of Pbrm1 increased the sensitivity of tumor cells to interferon-γ and made tumor cells more susceptible to T-cell-mediated killing." (PMID 38305770, 2024). "Both shared common features, such as the hypermethylation of functional regions in the genome, enrichment for somatic driver mutations (SETD2 and PBRM1), and associations with tumour stage, grade, and overall survival." (PMID 39592856, 2024). "The panel NGS of the primary tumor revealed pathogenic mutations in PBRM1 and PTEN and likely pathogenic mutations in VHL as well as PIK3C2G." (PMID 38611655, 2024). "Altogether, these results suggest MCL1 inhibition, either directly or indirectly through CDK9 inhibition, has potent anti-tumor activity in PBRM1-deficient ccRCC." (PMID 38371625, 2024). "Consistent with a tumor-suppressive function, PBRM1-deficient ccRCC tumors upregulate hypoxia-inducible factor and angiogenesis pathway transcription to enhance tumor vascularity." (PMID 38460939, 2024). "A higher load on R-loops was noted in tumor cells with PBRM1 deficiency, which contributes to increased replicative stress and DNA damage." (PMID 37175555, 2023). "Mutations in the PBRM1 gene have been shown to contribute to the development of tumors by inhibiting the ability of natural killer cells to clear tumor cells." (PMID 37762031, 2023). "Loss of VHL is often associated with loss of other tumor suppressor genes including PBRM1, BAP1 and SETD2, which are also located on chromosome 3p." (PMID 37173966, 2023). "Already in 2013, the genome of the clear cell RCC was identified, which is characterized by the absence or mutation of the VHL tumour suppressor gene (localized at 3p25) and frequent inactivation of the chromatin-modifying genes PBRM1, BAP1 and SETD2." (PMID 36672289, 2023). "Another frequently mutated gene, polybromo-1 (PBRM-1), plays a critical role in chromatin remodeling and tumor suppressor function." (PMID 38002445, 2023). "In cancer, PBRM1 acts primarily as a tumor suppressor, and loss of PBRM1 was previously associated with the deregulation of expression of apoptotic and cell cycle regulatory genes, as well as the metabolism-related markers and cell adhesion molecules." (PMID 36674511, 2023). "Recently, biomarkers that reflect the effects of various ICIs, such as tumor cell PD-L1 expression, tumor mutational burden, neoantigen burden, polybromo-1 gene mutation, immune cell infiltration, and intestinal microbiota, have been investigated." (PMID 36983417, 2023). "Clonality and a high proportion of cells harboring this PBRM1-deficient alteration were associated with tumor responses." (PMID 37446319, 2023). "Since the fact of the high frequency of mutations and loss of expression of PBRM1 in tumor, one approach for developing new therapy options in ccRCC would be to identify targets that have synthetic lethal relationships with PBRM1 loss." (PMID 35719970, 2022). "That is, VHL mutation acts as an initiative event to induce tumor occurrence, while PBRM1, BAP1 and SETD2 cause DNA repair defect and cell overgrowth." (PMID 35918352, 2022). "Patients with tumours harbouring PBRM1 mutations appeared to have a shorter DFS, although this was not significant (p = .093) in this small cohort." (PMID 36178086, 2022).